TNF (tumor necrosis factor)
Diseases named in the same sentence as TNF in open-access papers (continued):
Sharing a sentence is not in itself a finding about the gene and the disease.
tumor (continued). "Moreover, we hypothesize that the tumor-promoting or anticancer response of TNF-α in the tumor microenvironment depends not only on the local concentration but also on its expression source in the tumor." (PMID 32149121, 2020). "Consequently, prophylactic TNF blockade might allow higher doses of checkpoint inhibitors thereby increasing their anti-tumor effects." (PMID 32486375, 2020). "Furthermore, the high tumor-infiltrating capability of TNF-α-treated tumor-specific Th9 cells may also contribute to their antitumor efficacy." (PMID 30717817, 2019). "Moreover, our findings indicated that when tumor cells interacted with stromal cells in the presence of pro-inflammatory stimuli, TNFα-induced p65 activation has led to elevated Notch1 expression and activation, which then gave rise to elevated production of CXCL8." (PMID 31105691, 2019). "In addition, chemotherapeutics modifies the levels of several cytokines, down-regulates immune suppressive cytokines (i.e., transforming growth factor-β (TGF β) and IL10), and up-regulates cytokines promoting tumor immunity (i.e., tumor necrosis factor-α (TNF-α), IL-2, and interferon (IFN)–γ)." (PMID 30991686, 2019). "In regard to tumor-suppressing roles, it could be shown that blockage of NF-kB, as well as Ras, leads to invasive epidermal neoplasia mediated by the activity of tumor necrosis factor/c-Jun N-terminal kinase (TNF/JNK)." (PMID 30917608, 2019). "Multiple cytokines, including tumor necrosis factor (TNF)-α, interleukin (IL)-6, IL-17, IL-12, IL-23, IL-10, transforming growth factor (TGF)-β, and macrophage migration inhibitory factor, have been associated with human cancers and can promote or inhibit tumor development." (PMID 31043452, 2019). "In addition to its direct influence on immunosuppressive TME, CAFs-derived IDO and PGE2 attenuate NK cells-mediated TNF-α and IFN-γ production, which may be associated with persistent fibrosis in HCC and tumor cell immune evasion." (PMID 31500650, 2019). "Furthermore, tumor-infiltrating mast cells colocalized with T cells, and tumor-derived TNF-α could induce immunosuppressive mast cells (PD-L1+ mast cells)." (PMID 30808413, 2019). "Secretion of sPD-1 after ICI treatment may be caused, at least partially, by enhanced production of cytokines such as IFN-α, IFN-γ, or TNF-α due to ICI-mediated anti-tumor response because altered levels of sPD-1 after treatment of ipilimumab corresponded to changes in the circulating cytokines." (PMID 31192215, 2019). "Therefore, in this study the relationship between IL23α and TNF-α expression, and anti-proliferative effect of AC-EF based tumor therapy remain unclear." (PMID 32695310, 2019). "In addition, the tumour expression of IL-10, TNF-α and TGF-β was analysed by RT-PCR." (PMID 31731436, 2019). "Moreover, our findings suggest that previous studies on TNFα-treated MSCs that induced anti-tumor activities in TNBC tumors may have overlooked the actual setting that takes place in vivo, when TNBC cells interact with MSCs in the presence of TNFα stimulation." (PMID 31031757, 2019). "To test this hypothesis, we treated TNFα-induced senescent SF for 72 h with fenofibrate, a PPARα agonist recently been reported to have potent senolytic and senomorphic activity in senescent chondrocytes and tumour cell lines." (PMID 31708994, 2019). "In addition, nanomelanin might indirectly induce apoptosis in tumor tissues via activation of TNF-α, Bax, and Caspase-3 genes." (PMID 31137873, 2019). "Moreover, GCs effect could be influenced by tumor size, stage and grade, GC doses, response to endocrine therapy and inflammatory signaling, such as an interaction with TNF as shown in our results." (PMID 30987626, 2019). "Taken together, these data suggest that MOv18 IgE may support TAM populations with mature phenotypes and hybrid M1/M2 features that are able to enter the tumour, trigger sustained immune activating pathways and secretion of IL-10, TNFα, MCP-1 and IL-1α in tumour-bearing lungs." (PMID 31544825, 2019).
tumor (continued). "According to the anticipated peri genetic mechanism, signaling molecules associated with inflammation,such as TNF-α, alter epithelial cell adhesion and lead to the dispersion and movement of mutated epithelial cells without the need for additional mutation in tumor suppressorgenes." (PMID 31831956, 2019). "Furthermore, tumor immune escape was also shown to be partially due to ILC1s production of TNFα." (PMID 31024531, 2019). "In addition, angiopoietin-2 (ANG-2) is able to recruit circulating Tie2-expressing monocytes (TEMs) that inhibit apoptosis in both tumor and endothelial cells, by mechanisms depending on TNFα release, and exhibits an essential pro-angiogenetic role with a not completely clarified mechanism." (PMID 31447834, 2019). "Similarly, blood cells also restrict tumor growth induced in the wing disc in a discs large mutant background, and in these mutant animals, plasmatocytes express Eiger (Egr), the Drosophila homolog of tumor necrosis factor (TNF)." (PMID 30733377, 2019). "In addition, TNF-α also regulates the inflammatory response and apoptosis of tumor cells." (PMID 31192265, 2019). "Thus, when retrieved from the tumor 12 days after their transfer, they presented a characteristic high surface expression of inhibitory receptors, diminished production of IFNγ and TNFα, and low cytolytic activity as well as the expression of the high-mobility group (HMG)-box TFs - TOX and TOX2." (PMID 31766350, 2019). "This may have been a result of the tumor cells upregulating heparanase in response to stimuli from the tumor microenvironment, which could include soluble factors such as TNF-α and IL-1β, or heparanase may have originated from other cell types within the tumor microenvironment (e.g., macrophages)." (PMID 31110966, 2019). "In addition, the survival of TNF knockout mice implanted with the tumor is significantly longer." (PMID 32232096, 2019). "Moreover, in a mouse model of breast cancer lung metastasis, MSCs that were pre-conditioned with TNFα and co-injected with tumor cells were shown to recruit CXCR2+ neutrophils by secreting CXCR2 ligands (CXCL1, CXCL2, and CXCL5), resulting in enhanced lung metastasis." (PMID 31428105, 2019). "Indeed, we and others have shown that in vitro tumor-conditioned tumor-associated macrophages (TAMs) exhibit a mixed M1/M2 macrophage phenotype, expressing both M2 (CD163 and CD206) and M1 (IL-1β, IL-6, TNF-α, and CCL3) markers." (PMID 30917934, 2019). "Thus, TNFα‐CSG treatment prior to imaging could potentially sensitise the tumours for improved accumulation of contrast agents, enabling better MRI contrast." (PMID 31709774, 2019). "In addition, only tumour cells that were activated with TNF-α, with modified cell morphology with increased elongated cells with pseudopodia indicating epithelial-mesenchymal transition (EMT), could be observed." (PMID 31565662, 2019). "In addition, PD-1/PD-L1 axis blockade might activate tumor-specific T lymphocytes to kill tumor cells by inducing TNF-α and IFN-γ." (PMID 31681606, 2019). "Indeed, the findings presented in the current study indicate that the elevated levels of migration and invasion of TNBC cells following their interactions with MSCs/CAFs in the presence of TNFα were mediated by Notch signaling, as these tumor cell functions were prominently inhibited by DAPT." (PMID 31105691, 2019). "Furthermore, TNFα and IFNγ in combination induce tumor cell senesce mediated by CD4+ T cells (Th1)." (PMID 30833945, 2019).
tumor (continued). "Several microRNAs were previously found to be released by tumor cells and interact with Toll-like receptors of immune cells, leading to their activation, accompanied by upregulation of NF-κB and secretion of the proinflammatory, prometastatic cytokines TNF-α and IL-6." (PMID 30611259, 2019). "TNFα could activate endothelium, facilitating leukocytes entry in the tumor." (PMID 31024531, 2019). "Furthermore, a considerably higher proportion of freshly-isolated CD68+ macrophages from dispersed rat lung tumours of rats administered rat MOv18 IgE were found to express intracellular TNFα, an M1 macrophage marker, compared to MOv18 IgG2b and vehicle-treated tumours." (PMID 31544825, 2019). "Among the analyzed cytokines, TNF‐α can induce fibroblasts to secrete protease and destroy the mesothelial layer, which leads to tumor invasion and the regulation of neutrophil gene expression that is related to promoting tumor invasion and migration (Demoulin, Herfs, Delvenne, & Hubert, 2013)." (PMID 31660141, 2019). "Activating mutations in oncogenic RAS/BRAF/MEK pathways trigger a tumor-intrinsic inflammatory network with the concerted regulation of master transcription factors (TFs) including STAT3, NF-κB and AP-1 which in turn trigger the expression of cytokines, including IL-6, IL-1, IL-10, TNF and VEGF." (PMID 31766350, 2019). "Studies demonstrate that tumor colonization by bacteria can induce proinflammatory reactions involving elevated expression of IL-1β, TNF-α, and IFN-γ, as well as NK and T-cell activation; therefore, a combination of ICB and bacterial therapies may overcome host resistance." (PMID 31827064, 2019). "In tumor cell lines, NF-κB has been furthermore established as a suppressive regulator of autophagy, in response to the cytokine TNFα, which may contribute to suppression of TNFα-induced apoptotic signaling and oxidative stress." (PMID 31906235, 2019). "When produced in the microenvironment of the tumor, TNFα may also act as tumor promoter." (PMID 31591350, 2019). "Tumor-infiltrating γδT17 cells could secrete IL-17, IL-8, TNF-α, and granulocyte macrophage colony-stimulating factor to promote the proliferation and survival of polymorphonuclear MDSCs, thus transforming the CRC-triggered inflammation into an immunosuppressive condition." (PMID 29997627, 2018). "However, many tumour cells develop resistance to the toxic effects of TNF‐α." (PMID 29632814, 2018). "Interestingly, ASPP2 KD, but not overexpression, increased the expression of CCL2, CCL5, and TNF-α and enhanced their secretion, which may promote macrophage recruitment to tumor tissues and support multiple aspects of tumor progression." (PMID 30389910, 2018). "Since apoptotic stimuli, such as proinflammatory TNF, chemotherapeutic daunorubicin, as well as ionizing radiation may be responsible for the anti-apoptotic role of NF-κB, it is important to inhibit NF-κB during cancer treatment to overcome tumor resistance." (PMID 30413032, 2018). "Besides, the dependence of the triple action of THPDTPI inhibiting the tumor growth, the thrombosis and the inflammation on the decrease of the soluble P-selectin led to the correlation of the soluble P-selectin with the serum TNF-α and serum IL-8." (PMID 29416612, 2018). "Interestingly, a significant increase in the serum concentrations of TNF and IL-6 was found in the P2Et/P2Et groups compared with the other groups in both tumor models, while in the P2Et/P2Et-treated B16 tumors, the serum concentrations of both IL-17 and IL-4 were significantly decreased." (PMID 30234017, 2018). "Also, TNF may favor tumor invasiveness and metastasis by stimulating matrix metalloproteinase production and vascular permeability." (PMID 29593717, 2018).
tumor (continued). "Additionally, in contrast to reports from Western countries, we did not observe associations between an increased risk of malignancy and thiopurine or anti-TNF-α antibody usage among patients with IBD, but steroid usage appeared to be associated with the risk of tumor development." (PMID 30373275, 2018). "Similarly, other authors have shown that ICAM-1 expression in mesothelial cells was increased by pre-incubation with TNF-α or IL-6, with a concurrent increase in tumour adhesion, which was then partially attenuated by the use of a monoclonal antibody against ICAM-1." (PMID 29772648, 2018). "However, considering several anticancer mechanisms of TNF, such as induction of tumor vessel obstruction and tumor immune surveillance, effects related to anti-TNFα agents may contribute to tumor development by suppressing the anticancer mechanisms of TNF." (PMID 29954352, 2018). "Importantly, TNFα treatment induced a significantly larger increase in spheroid degradation compared to tumor growth suggesting that TNFα may primarily affect degradation mechanisms and not cell growth rate." (PMID 30356830, 2018). "High Wg activity could therefore be one of the factors rendering tumours insensitive to TNF-α." (PMID 29725601, 2018). "Moreover, gel-liquid approach has enabled cell migration studies in response to specific cytokines such as tumour cell intravasation (i.e., migration towards blood vessels) under TNFα exposure or tumour cell extravasation (i.e., migration from blood vessels) under chemokine CXCL5." (PMID 30214484, 2018). "Similarly, in tumor immunology, TNFα can mediate opposing effects." (PMID 30305177, 2018). "Furthermore, several pro-inflammatory cytokines, including members of the Tumor Necrosis Factor (TNF)-superfamily, that are produced in the tumor microenvironment are known to modulate the survival and migration of both tumor and surrounding cells and thus promote cancer development and metastasis." (PMID 30002278, 2018). "However, in these cell lines, TNF‐α stimulation promoted the expression of miR‐130b and downregulated the expression of PTEN gene, which encodes a dual‐specificity phosphatase that acts as a tumour suppressor." (PMID 29632814, 2018). "The demonstration of antagonistic actions of TNF-α in Drosophila and mammalian tumours suggests that the successful use of antitumoural immunity as a cancer therapy may strongly depend on, and must take into consideration, the genetic composition of the tumour." (PMID 29725601, 2018). "Distinct from tumor-derived exosomes, these immune cell-derived exosomes activate the immune response primarily through the TNF-α pathway, which may then induce epithelial cells to secrete other pro-inflammatory cytokines, such as IL-8, RANTES, and additional TNF-α." (PMID 30108680, 2018). "The authors believe that by selectively removing soluble TNF-alpha receptors local enhancement of endogenous TNF-alpha activity may provide for enhanced tumor cell death without associated systemic toxicities." (PMID 30170620, 2018). "Neutrophils could be stimulated to proliferate by cancer-related inflammatory factors, such as Tumor necrosis factor-alpha and Interleukin-6, which subsequently secrete reactive oxygen species and pro-angiogenic factors, and therefore favors tumorigenesis and tumor microenvironment." (PMID 29940884, 2018). "Thus, we hypothesised that the kinetics of hyperpolarised pyruvate transport and metabolism may change within the tumour-bearing hemisphere when TNF was administered." (PMID 30305655, 2018). "Additionally, the TG2 gene has regulatory elements that respond to cytokines, including TGF-β, interleukin 6 (IL-6) and tumor necrosis factor alpha (TNF-α), suggesting that the tumor microenvironment may also have a role in increased TG2 expression." (PMID 30200219, 2018).
tumor (continued). "Asialyl-agalactosyl IgG, as its effect on the activation of tumor-associated macrophages, upregulated tumor-associated macrophage-related cytokines including interleukin (IL)-4, IL-10, transforming growth factor (TGF)-β1, and tumor necrosis factor (TNF)-α, in macrophagic U-937 cells." (PMID 30469416, 2018). "Consequently, in addition to changes in the local tumor microenvironment, changes in levels of peripheral inflammatory factors, such as tumor necrosis factor (TNF), interleukin (IL)-1, -6, and -8, and vascular endothelial growth factor (VEGF), also promote tumor growth and metastasis." (PMID 28187463, 2017). "Thus, proliferation of tumor cells independent of PTEN status was significantly reduced in the presence of IFNγ- and TNFα-activated astrocyte-CM compared to normal culture media or to CM from co-cultures of astrocytes with tumor cells (231BR/CTL and 231BR/PTEN: p < 0.001)." (PMID 28008153, 2017). "Interestingly, when we analyzed the expression of macrophage chemotactic cytokines produced by tumor cells in the xenograft model, we observed a significant increase in human GM‐CSF and human TNFα levels after PLX4720 exposure independently from bevacizumab treatment." (PMID 27974353, 2017). "In addition, we find that systemically applied immunostimulatory agents such as oncolytic VSV or recombinant IFN-α can result in increased TNF-α in the brain to potentially kill tumours with SMCs, releasing tumour antigens and stimulating inflammatory and immunomodulatory responses." (PMID 28198370, 2017). "Although TNFα and IFNγ both increased PD-L1 expression (4202 ± 2500 and 4724 ± 4155, respectively), it was only the combination TNFα/IFNγ (25818 ± 14131, p < 0.0001) that resulted in a significant increase in PD-L1 expression in tumor-derived Lin-EpCAM-CD73+CD90+ cells." (PMID 28878242, 2017). "Cytokine profiling of the primary tumour identified human IL-6 and TNF-α – consistent with the corresponding murine factors found in the mouse tissue, and indicative of pro-inflammatory response – but also a range of other factors that could be derived from both innate and adaptive immune cells." (PMID 28417956, 2017). "Second, unlike genes essential for tumor growth or survival for which expression is constitutively upregulated, the expression of TNFα may be more transient and associated with inflammatory stimuli." (PMID 29018206, 2017). "In addition, by releasing proinflammatory cytokines, such as tumor necrosis factor-alpha (TNF-α), interleukin (IL)-6, and vascular endothelial growth factor (VEGF), tumor cells and tumor-associated leukocytes play a direct role in promoting proliferation and metastasis." (PMID 28358923, 2017). "Inhibition of NF-κB activation reduced cisplatin nephrotoxicity without affecting its oncolytic action, which might be explained by the observation that cisplatin nephrotoxicity was mediated via TNFR2, whereas the anti-tumor effect of TNF-α was mediated by TNFR1." (PMID 28182789, 2017). "IHC analysis on type 1 EC showed that the selected adipokines are differently expressed within the tumor; staining could be located in the cytoplasm of EC cells (TNF α and RBP4), in the cytoplasm of stromal cells (adiponectin) or both in EC and stromal cells (IL-6 and SPARC)." (PMID 28505082, 2017). "Real-time RT PCR assay showed that the levels of TNF-α and IL-1β, pro-inflammatory cytokines known as important factors for tumorigenesis, were elevated in extra- and intraorbital lacrimal glands receiving A20 cells, reflecting an inflammatory milieu in tumor-bearing glands." (PMID 29029511, 2017). "Interestingly, metformin, another well-known anti-diabetic drug, showed similar antitumor effect through inducing the number of CD8+ tumor-infiltrating lymphocytes (TILs) and protected them from apoptosis and exhaustion characterized by decreased production of IL-2, TNF-α, and IFN-γ17." (PMID 28496193, 2017).